BUB1B (BUB1 mitotic checkpoint serine/threonine kinase B)
Diseases named in the same sentence as BUB1B in open-access papers (continued):
Sharing a sentence is not in itself a finding about the gene and the disease.
tumor (continued). "Furthermore, we show that YY2/BUB1B axis‐induced mitotic checkpoint hyperactivation triggers chromosome missegregation and cytosolic dsDNA, thereby inducing cytosolic dsDNA response and promoting tumor immunity." (PMID 39903759, 2025). "Therefore, future studies on BUB1 and BUB1B combining genetic approaches may provide an effective strategy for clinical anti-tumor treatment and could be the focus of SCLC research in the future." (PMID 33186389, 2020). "Moreover, overexpression of CDK1, CCNB1, CDC20, BUB1, MAD2L1, and BUB1B in tumour tissues could increase cell proliferation and division." (PMID 33035258, 2020). "Since reduced BUB1B expression has been associated with decreased tumor metastasis in our animal studies, we interrogated whether BUB1B knockdown would sensitize cells to anoikis, thereby explaining, at least in part, the observed inhibition of tumor metastasis." (PMID 26000094, 2015). "The analysis revealed that the five key genes, including BUB1, BUB1B, CDK1, UBE2C, and CCNA2, exhibited higher expression in LUAD tumor tissues compared to normal tissues in all cases." (PMID 41181148, 2025). "Specifically, BUB1B was found to be upregulated in LUAD, correlating with clinical diagnosis and prognosis and tumor immunity." (PMID 40076684, 2025). "In lung adenocarcinoma, BUB1B was found to impair the SAC in mitosis and promote tumor cell proliferation and metastases." (PMID 41163302, 2025). "The discovery that CDK1, TOP2A, AURKA, TPX2, BUB1B, and CENPF are key cell-cycle regulators in NSCLC emphasizes the ongoing contribution of mitotic dysregulation to tumor growth." (PMID 41080754, 2025). "Moreover, we explored whether BUB1B was involved in YY2‐induced anti‐tumor immune response." (PMID 39903759, 2025). "In BALB/c nude mice bearing subcutaneous tumors that overexpress BUB1b, a combined strategy of ML385 targeting and chemotherapy achieved synergistic effects, inhibiting tumor growth and obviously improving survival." (PMID 39043653, 2024). "For instance, BUB1B, a crucial serine/threonine kinase in the mitotic checkpoint pathway, acts as an oncogenic role in HCC tumor growth and metastasis via activating mTORC1 and JAK-STAT signaling pathways." (PMID 39624268, 2024). "Further analysis showed that overexpression of BUB1B, BUB1 and BUB3 promoted tumor cell proliferation and metastases by disturbing the spindle assembly checkpoint (SAC) in the mitosis." (PMID 37228122, 2023). "Four hub genes, including TTK, BUB1B, NUSAP1, and ZWINT, were revealed as tumor-promotive factors in OC, having the potential to be utilized as novel biomarkers and therapeutic targets for OC management." (PMID 37304238, 2023). "Of the SAC genes overexpressed in the OB tumor cells, TKK, PLK1, CDK1, BUB1 and BUB1B have been shown to play a role in radiosensitivity." (PMID 36482431, 2022). "BUB1B deletion suppressed LUAD malignancy in vitro and inhibited tumor growth in vivo through regulating glycolysis." (PMID 35068350, 2022). "Knocking-out BUB1B resulted in suppression of BUB1B LUAD malignancy in vitro and inhibition of tumor growth in vivo." (PMID 35068350, 2022). "It has been found to have highly expressed in tumor tissues and HCC cell lines, and BUB1B knockdown significantly inhibited the proliferation, migration, and invasion of HCC cells." (PMID 36171884, 2022). "In summary, our findings demonstrate that BUB1B is regulated by ZNF143 and that the ZNF143-BUB1B axis is likely to regulate the development and progression of tumor through glycogen metabolism signaling." (PMID 35068350, 2022).
tumor (continued). "In summary, we suppose that HDAC2 regulates the expression of BUB1B in NPC to participate in the occurrence and progression of tumor." (PMID 36577966, 2022). "Of note, we found BUB1B/BUBR1 as the most upregulated protein in CRT-recurrent tumor as compared with the primary treatment-naïve tumor and immunoblotting from the corresponding samples confirmed the upregulation of BUB1B/BUBR1 in CRT-recurrent tumor." (PMID 34545188, 2021). "The presence of another mitotic marker, phosphorylated BubR1/BUB1B, strongly indicates that UA62784-treated tumor cells undergo mitotic arrest due to activated spindle assembly checkpoint (SAC)." (PMID 34094924, 2021). "The results showed that the knockdown of BUB1B inhibited the migration of CCA cells, while overexpression of BUB1B contributed to tumor cell migration in wound-healing assay." (PMID 33431813, 2021). "MGI is a gene expression assay, measuring the expression of five genes (BUB1B, CENPA, NEK2, RACGAP1, RRM2) related to histological grade and tumor progression, which recapitulates tumor grade and can predict the clinical outcome with high performance." (PMID 33287297, 2020). "In conclusion, we found that CENPF, BUB1, BUB1B, KIF23 and TTK were potential key genes involved in regulating hypoxia induced tumor cell stemness." (PMID 33148251, 2020). "Further clinical validation of the tumor promoter and worse prognosis predictor function of NDC80 and MAD2L1 in local LUAD and LUSC patients as well as the genes’ relation with BUB1B and AURKA is on our way." (PMID 32795325, 2020). "Top hub genes of the black (M7) module BUB1B and CENPF are reported to contribute to the tumor microenvironment." (PMID 31628349, 2019). "In this research, we further assessed the differential expression of five hub genes (TPX2, KIF2C, CDCA8, BUB1B, and CCNA2) in various clinical stages, and the results showed that their expression was significantly increased in advanced tumour stages." (PMID 31285741, 2019). "BUB1B, CCNB1, CDC7, CDC20, and MCM3 were all overexpressed in HCC patients with neoplasm histologic grade G3-4 compared to those with G1-2 (all P < 0.05)." (PMID 30363964, 2018). "Upregulated BUB1B, CCNB1, CDC7, CDC20, and MCM3 in HCC tumor tissues also contributed to worse DFS in HCC patients (Log rank P = 0.000052, 0.0192, 0.0307, 0.00496, and 0.0284, respectively)." (PMID 30363964, 2018). "BUB1B, CCNB1, CDC7, CDC20, and MCM3 were significantly increased in HCC patients with neoplasm histologic grade G3-4 compared to those with G1-2 (all P < 0.05)." (PMID 30363964, 2018). "It has been reported that PLK1 also interacts with other tumor suppressors such as CHK2, BRCA1/2, ATM and ATR, BUB1B or BUBR1, CYLD, REST, and TSC1/2." (PMID 28953239, 2017). "To investigate the effect of BUB1B knockdown in vivo, we implanted the LKPH2 inducible shRNA stable cell lines subcutaneously into nude mice and measured primary tumor volumes as well as metastases in the lung and lymph nodes." (PMID 26000094, 2015). "Surprisingly, that study also showed that let-7 represses several tumour suppressor genes (BRCA1, BRCA2, FANCD2, and PLAGL1, among others) and checkpoint regulators (CHEK1, BUB1, BUB1B, MAD2L1, and CDC23, among others)." (PMID 20179807, 2010). "Next, we explored whether BUB1B‐mediated chromosome missegregation was involved in YY2‐induced cytosolic dsDNA response, pyroptosis, and tumor immune response." (PMID 39903759, 2025). "Moreover, the YY2/BUB1B axis is crucial for promoting CTL proliferation and activation within tumor lesions, thereby enhancing the anti‐tumor immune response." (PMID 39903759, 2025). "Moreover, the relationships among BUB1b, NRF2, and GPX4 were further investigated via IHC staining in a TMA containing 92 LUAD tumor tissues and matched paratumor tissues." (PMID 39043653, 2024).
tumor (continued). "IHC staining of BUB1b was also performed in tissue samples and tissue microarray (TMA) containing 92 LUAD tumor tissues and matched para tumor tissues, and BUB1b was significantly highly expressed in tumor tissues." (PMID 39043653, 2024). "In the TCGA-HCC dataset, 13 genes were identified with significant correlation with SAMD13 from the tumor group only and a total of six genes including FOXM1, JUN, JARID2, BRE, BUB1B, and PHC2 were shown to significantly predict poor overall survival in log-rank tests in HCC." (PMID 37968735, 2023). "Moreover, the expression levels of BUB1, BUB1B, CDK1, CCNA2, MCM10 were significantly higher in CRC tumor tissues compared with normal tissues based on the GEPIA database." (PMID 37466419, 2023). "BUB1B deletion suppresses LUAD malignancy in vitro and inhibits tumor growth in vivo." (PMID 35068350, 2022). "To explore the expression profiles of BUB1B in CCA, we first examined the expression in CCA patients from a public TCGA database and found that BUB1B was overexpressed in CCA tissues compared to para-tumor." (PMID 33431813, 2021). "After the orthotopic inoculation, all the cells including T24-ATM+/+ and T24-ATM−/− BC cells with or without BUB1B/BUBR1 stable overexpression uniformly developed tumor with no significant growth difference when no treatment was offered." (PMID 34545188, 2021). "The distribution of BUB1B and CCNA2 expression correlated with tumor stage." (PMID 34253236, 2021). "According to the CPTAC data, the protein expression of PKMYT1, ETF1, ECT2, BUB1B, and RECQL4 in tumor tissues was significantly increased, while the expression of TFRC was significantly reduced, and the expression of COCH and TUBB2B did not change significantly (PITX1 and CDC6 were not included)." (PMID 33869220, 2021). "Increased BUB1B/BUBR1 protein-expression level in CRT-recurrent tumor seemed to be evident compared with the normal bladder and primary tumor tissue, and mRNA expression level was also significantly upregulated in the CRT-recurrent tumor." (PMID 34545188, 2021). "In our present study, we evaluated the expression of BUB1B in HCC using TCGA, GEPIA, IHC, qRT‐PCR, and western blotting, and subsequently validated its overexpression in the tumor tissues and adjacent normal tissues from patients suffering from HCC and HCC cell lines." (PMID 32977361, 2020). "To explore the specific function of BUB1B in HCC in vivo and in vitro, we performed the flow cytometry, Cell Counting Kit‐8, 5‐ethynyl‐2′‐deoxyuridine incorporation, colony formation, Transwell, wound‐healing, subcutaneous tumor growth, and metastasis assays." (PMID 32977361, 2020). "Similarly, BUB1B and CDC20 were both significantly up-regulated in PDAC patients with new tumor development after initial treatment (both P<0.05)." (PMID 30765611, 2019). "In addition, PDAC patients with neoplasms of histologic grade G3-4 had significantly higher BUB1B, CCNA2, and CDC20 levels than those with grade G1-2 neoplasms (all P<0.05), and high levels of BUB1B and CDC20 contributed to tumor formation (both P<0.05)." (PMID 30765611, 2019). "So, BUB1B may reduce the recognition of immune cells by reducing the expression of immunogenetic molecules, thereby promoting tumor progression and deteriorating prognosis, which is not conducive to survival." (PMID 40076684, 2025). "In addition, it was showed that the clinicopathological feature between BUB1B and RRM2 genes expression and HCC patients were significantly changed in age, fibrosis Ishak score, neoplasm histologic grade, pathologic T, race and tumor stage diagnoses." (PMID 36829489, 2023). "Moreover, a significant relationship between CTLA-4 and BUB1B expression in HCC, suggesting that tumor immune evasion may influence the hepato-carcinogens that BUB1B mediates." (PMID 36829489, 2023).
tumor (continued). "We subsequently evaluated the detailed expression level of BUB1B in various clinical futures of patients by quantitative analysis, and the results showed that patient's age, gender, T stage, N stage, M stage, clinical stage, neoplasm depth, length, and width did not influence BUB1B mRNA expression." (PMID 35517426, 2022). "However, BUB1, CCNB1, BUB1B, KIF11, CDC20, TTK, and NCAPG, which are closely related to regulation of the cell cycle and DNA repair, showed strong positive correlations with tumor purity in luminal-type BC." (PMID 34733851, 2021). "Interestingly, from these 17 significant pairs (adjusted p-value ≤ 0.05) several downregulated tumour-suppressor miRNAs (e.g., miR-let-7c, miR-139, miR-145 or miR-195) appeared to regulate oncogenic genes related to the cell cycle and DDR pathways (BUB1B, AURKA, BIRC5, CENPK, BRCA1 and CHEK1)." (PMID 28387377, 2017). "Using a combined geneset of these 5 remaining cell cycle-related genes (BUB1B, CCNB1, CCNB2, TTK and CDK1) as well as ADAM7 and FAM72B, we also observed a statistically-significant reduction in disease-free survival of patients with tumours exhibiting alterations in gene expression (p = 0.015)." (PMID 25519703, 2014). "Overall, we identified CENPF, BUB1, BUB1B, KIF23 and TTK as potentially key genes involved in regulating hypoxia-induced tumor cell stemness, and found that AC079160.1-miR-539-5p-CENPF axis may be involved in regulating hypoxia induced tumor cell stemness in LUAD." (PMID 33148251, 2020). "Whereas the predicted increases of Bub1b and Mad2 were detected in the OB for NSC11 tumor cells, no change in protein levels were detected in NSC20 tumors." (PMID 36482431, 2022). "Although BUB1B and CENPE have not been reported to be involved in tumour immunity, their functions in the TME warrant further research." (PMID 34631565, 2021).
infection (9 papers, 2009 to 2026). The state of being infected such as from the introduction of a foreign agent such as serum, vaccine, antigenic substance or organism. "A group of Treg-signature genes (Areg, Arhpag20, Bub1b, Ccl12, Ccr5, Il1r1, Mki67 (Ki67) Ncf1, Nrp2, Tnfrsf9, Tcf19, Uhrf1, and Wnt3) were expressed at higher levels in IFNARfl/fl x Foxp3YFP-Cre mice than WT controls on day 5 Armstrong infection." (PMID 29672594, 2018). "Additionally, as the duration of infection increases, aging-related genes Plk1, Cenpa, Bub1b, H2afx, and Cdkn2d were activated, suggesting that infection may initiate cellular senescence." (PMID 41827050, 2026). "In response to infection, in male mice, the TACC2, BUB1B, ATP5MC3, and MYO1E, and in female mice, the CAP1, MRPL2, COX5A, KLHL21, PDIA6, TSPO, and USP14 had direct interaction with TP-53." (PMID 35844510, 2022). "Genes that were down-regulated genes at 24h post infection included inflammatory and anti-pathogen genes (CSF1 and USP2) and the cell apoptosis and death genes (MICB, BUB1B, ITGB2, UBB and BIRC3)." (PMID 23527143, 2013).
genetic disorder (2 papers, 2020 to 2024). "Mosaic variegated aneuploidy (MVA) is a rare genetic disorder caused by mutations in BUB1B, CEP57, or TRIP13." (PMID 32884756, 2020).
kidney disease (1 paper, 2025). "To validate the potential genes is functionally in kidney disease, we choose whole genes (CDC16, CDC20, CDC27, MAD2L1, ANAPC1, ANAPC7, BUB1B) from first highest score subnetwork obtained from Cytoscape MCODE plugin from upregulated genes PPI as hub genes." (PMID 40034749, 2025).
BUB1B also shares sentences with these, for which no sentence is quoted: cataract (8 papers); gastric adenocarcinoma (4); lymph node metastasis (4); progeria (4); breast tumor (3); candidiasis (3); clear cell kidney carcinomas (3); esophageal cancer (3); Infertility (3); neuroblastoma (3); adenocarcinoma (2); aneuploidy (2); cognitive decline (2); colorectal tumors (2); ductal breast carcinoma (2); esophageal squamous cell carcinoma (2); Intellectual disability (2); kidney cancer (2); lung (2); mesothelioma (2); Oral leukoplakia (2); oral squamous cell carcinoma (2); osteoporosis (2); Pan (2); prostate adenocarcinoma (2); thyroid cancer (2); Wilms tumor (2); abortion (1); acute lymphoblastic leukemia (1); adrenal carcinoma (1).
A further 73 diseases each share a sentence with BUB1B in 1 paper.